RB1 (RB transcriptional corepressor 1)
Diseases named in the same sentence as RB1 in open-access papers (continued):
Sharing a sentence is not in itself a finding about the gene and the disease.
retinoblastoma (continued). "This advantage is due to a specific requisite genetic change in the etiology of the vast majority of Rb tumors: the loss of functioning retinoblastoma protein (pRb) often due to mutation or epigenetic silencing of its coding gene, RB1." (PMID 23826078, 2013). "For example, homozygous inactivation of the RB1 gene causes the childhood eye cancer retinoblastoma." (PMID 23840359, 2013). "Previous studies have shown that human RB1-deficient retinoblastoma cells have defects in sister chromatid cohesion consistent with previously published data on cultured human RPE cells with RB1 depletion." (PMID 23765217, 2013). "Inactivation of both alleles of the RB1 gene in a single immature retinal cell can trigger retinoblastoma tumorigenesis." (PMID 23441118, 2013). "In Knudson’s two-hit theory of tumorigenesis, which was developed to understand the pathogenesis of retinoblastoma, the tumor is thought to arise due to loss of function at both loci of the tumor suppressor gene, RB1." (PMID 23951062, 2013). "Retinoblastoma results from RB1 gene inactivation and loss of pRB1, yet the proliferation and metastasis that underlie retinoblastoma development have not been well defined." (PMID 23559850, 2013). "Retinoblastoma is initiated by inactivation of both RB1 alleles encoding the protein, pRB that controls cell proliferation, differentiation and genomic stability." (PMID 22336108, 2012). "We have identified mutations in the zebrafish space cadet locus that lead to a premature truncation of the rb1 gene, identical to known mutations in sporadic and familial forms of retinoblastoma." (PMID 23209449, 2012). "Like p16INK4, loss of RB1 function by genetic deletion is commonly seen to be an essential process of oncogenesis in wide ranges of human malignancy, such as retinoblastoma, breast cancer, and small cell carcinoma of the lungs." (PMID 22619677, 2012). "Mutations in the retinoblastoma tumor suppressor gene (rb1) cause both sporadic and familial forms of childhood retinoblastoma." (PMID 23209449, 2012). "Here, we report that zebrafish space cadet mutants carry a rb1 mutation found in cases of sporadic and familial human retinoblastoma." (PMID 23209449, 2012). "Mutation of the retinoblastoma tumor susceptibility gene (RB1) is the rate-limiting step in the genesis of retinoblastoma and over 90% of human tumors exhibit reduced pRB function." (PMID 22496667, 2012). "Retinoblastoma (Rb), the most common childhood tumor of the eye, is caused by the inactivation of both alleles of the retinoblastoma 1 (Rb1) gene." (PMID 23049239, 2012). "Biallelic mutations in the retinoblastoma susceptibility gene rb1 are causal for intraocular childhood retinoblastomas." (PMID 23209449, 2012). "Children diagnosed with the hereditary form of retinoblastoma (Rb), a rare eye cancer caused by a germline mutation in the RB1 tumor suppressor gene, have excellent survival, but face an increased risk of bone and soft tissue sarcomas." (PMID 23036192, 2012). "Heritable retinoblastoma and osteosarcoma were found to be associated in some cases with the deletion of the 13q14 locus of the RB-1 gene." (PMID 21826516, 2011). "Clinical and genetic evaluations of the family members revealed that only four of the 11 individuals who carried the p.V654L mutation in one RB1 allele developed unilateral retinoblastoma, yielding a penetrance of only 36%." (PMID 21615945, 2011). "Retinoblastoma is caused by compound heterozygosity or homozygosity of retinoblastoma gene (RB1) mutations." (PMID 21615945, 2011). "In this study, we screened the RB1 germline mutations in 41 unrelated Moroccan patients with retinoblastoma, 25 heritable cases, and 16 sporadic unilateral cases." (PMID 22219649, 2011).
retinoblastoma (continued). "Only four individuals, including the index case (two males and two females), developed unilateral retinoblastoma (the members in solid black), and seven asymptomatic subjects carry a germ-line mutation in one RB1 allele (the members with the slanted line)." (PMID 21615945, 2011). "Retinoblastoma (RB), the most common intraocular tumor occurring in infancy and early childhood, is most often related to mutations in the RB1 gene." (PMID 22219649, 2011). "In germline retinoblastoma, mutations in the RB1 gene predispose individuals to increased cancer risks during development." (PMID 21615945, 2011). "This study describes a large Taiwanese family with retinoblastoma, with the germline RB1 p.V654L mutation." (PMID 21615945, 2011). "Despite over two decades since loss of RB1 was implicated in initiating retinoblastoma, the unique tissue specificity of this process remains puzzling." (PMID 20421947, 2010). "Approximately 90% of children carrying a germline mutation in RB1 will develop retinoblastoma during their early childhood." (PMID 20664703, 2010). "The variety of different genetic events underlying LOH at the RB1 locus in retinoblastoma seems to occur in lung cancer." (PMID 21151896, 2010). "For example, compared with children who are born with a normal, intact RB1 gene, those born with a germinal mutation in one of the two RB1 alleles have an enhanced risk of developing retinoblastoma (RB), a childhood ocular malignancy." (PMID 20406436, 2010). "We herein describe a novel constitutive mutation at the 5' UTR of RB1 in a patient with bilateral retinoblastoma, who also carried two other constitutive mutations also present in two of her sisters conceived by IVF." (PMID 19640284, 2009). "Mutations of the RB1 gene can result in either malignant retinoblastoma (RB; OMIM 180200) or benign retinoma." (PMID 19390654, 2009). "Clinical features and mutations description of 17 affected patients with hereditary retinoblastoma and/or retinoma harboring RB1 mutations." (PMID 19390654, 2009). "The novel mutation, affecting the Kozak consensus at the 5'UTR of RB1 and g.174351T>A were likely associated to retinoblastoma in the proband." (PMID 19640284, 2009). "Patients with hereditary retinoblastoma harboring a mutation in RB1 are at increased risk of developing pineoblastoma, supratentorial PNET and there is one case report of a medulloblastoma in such a patient." (PMID 18769486, 2008). "As opposed to breast cancer, there is a great deal known about the mechanisms of RB1 loss in retinoblastoma." (PMID 18782450, 2008). "There is an increased risk for the development of a metachronous malignancy following hereditary retinoblastoma due to the prior treatment and/or genetic susceptibility of RB1." (PMID 19077296, 2008). "RB1 germline mutations in individuals with hereditary or bilateral retinoblastoma are associated with an increased risk of sarcoma development later in life." (PMID 18784837, 2008). "Hereditary retinoblastoma constitutes a cancer predisposition syndrome: a subject constitutionally carrying an RB1 gene mutation has a greater than 90% risk of developing retinoblastoma but is also at increased risk of developing other types of cancers." (PMID 16934146, 2006). "Children who inherit one defective copy of the RB1 gene have an increased susceptibility to retinoblastoma." (PMID 16672052, 2006). "Individuals with bilateral retinoblastoma (and presumed germ line RB1 mutations) develop an average of five retinoblastoma foci, generally within their first 2 years, but have only ~1% per year likelihood of developing all other tumor types." (PMID 17163992, 2006). "Whereas RB1 is also inactivated in other tumors, the cells that give rise to retinoblastoma are exceptionally sensitive to Rb loss." (PMID 17163992, 2006). "Germinal RB1 mutations with a high penetrance rate (> 90%) concern all patients with bilateral retinoblastoma as well as 15% of patients with the unilateral form." (PMID 16934146, 2006).
retinoblastoma (continued). "The presence of RB1 germ line mutations confers an increased risk for development of second primary tumors in the survivors of hereditary retinoblastoma, with a cumulative incidence of 22% at the age of 25 years." (PMID 16269091, 2005). "Attempts by several groups to define the mutations resulting in the inactivation of the RB1 gene in retinoblastoma have led to the identification of a broad spectrum of mutations." (PMID 16269091, 2005). "In sporadic retinoblastoma, acute mutations are believed to occur at both RB1 loci; in heritable retinoblastoma, one allele has a germline disruption and the other undergoes acute inactivation." (PMID 16231976, 2005). "Experimental data show that in vitro methylation of the RB1 promoter region reduces pRB expression and unilateral retinoblastoma frequently shows loss of pRB expression associated with aberrant methylation of CpG island within the RB1 promoter region." (PMID 12556968, 2003). "The RB1 gene mutation was investigated in a child with ectopic intracranial retinoblastoma using DNA obtained from both the pineal and retinal tumours of the patient." (PMID 9400934, 1997). "Sixty-nine primary soft tissue tumours were examined for alterations of the RB1 gene which has previously been implicated in the genesis of retinoblastoma." (PMID 2765366, 1989). "Finally, in retinoblastoma, the loss of RB1 alone appears to induce benign, hypoproliferative retinoma, but additional oncogenic insults are required to transform these cells into highly aggressive tumors." (PMID 40075567, 2025). "Though uncommon in retinoblastoma, the presence of both RB1 and BRAF mutations could theoretically result in a more aggressive tumor phenotype." (PMID 40317918, 2025). "Knudson’s two-hit hypothesis states that both alleles of the RB1 gene must be mutated to convert normal retinal cells into neoplastic retinoblastoma cells." (PMID 40001157, 2025). "The study found that 48 distinct mutations in the RB1 gene caused retinoblastoma in 56 patients." (PMID 40317918, 2025). "Germline pathogenic alterations in the RB1 gene cause heritable retinoblastoma." (PMID 41009976, 2025). "However, GEMMs often require additional genetic alterations beyond RB1 loss (e.g., p107 or p130 deficiency) to reliably induce retinoblastoma, raising concerns about their fidelity to human disease." (PMID 40943594, 2025). "In contrast, MYCN-amplified retinoblastoma usually lacks RB1 mutations entirely." (PMID 41009976, 2025). "The RB1 gene shows a wide spectrum of pathogenic variants, with more than 500 distinct somatic and germline mutations identified to date that can give rise to retinoblastoma." (PMID 41002743, 2025). "Heritable retinoblastoma, by contrast, results from a germline RB1 mutation and may occur in familial or sporadic (de novo) forms." (PMID 41002743, 2025). "Loss of functional RB1 primarily leads to the development of retinoblastoma." (PMID 41009976, 2025). "Retinoblastoma 1 is another tumour suppressor gene that encodes the pRb protein, which controls cell cycle progression and prevents uncontrolled cell division; mutations in RB1 are the primary cause of retinoblastoma, an eye cancer typically occurring in children." (PMID 40724564, 2025). "In these studies, PBs were subdivided into two large subgroups: PB-A, clustered together with retinoblastoma, consisted of patients who are diagnosed as “intracranial retinoblastoma” including children with RB1 germline mutation; and PB-B, whose underlying biology was undetermined." (PMID 40075567, 2025). "Retinoblastoma was one of the first malignant tumors to be described as a genetic disease and its development occurs from the loss of function of the retinoblastoma gene (RB1)." (PMID 40332023, 2025). "Bilateral retinoblastoma cases almost always harbor germline RB1 mutations, while ~15% of unilateral cases may also carry germline or mosaic mutations." (PMID 41009976, 2025).
retinoblastoma (continued). "While bilateral retinoblastoma patients almost always harbor a germline RB1 pathogenic mutation, notably, approximately 15% of unilateral cases, including those with no family history, are also associated with germline or mosaic RB1 pathogenic variants." (PMID 41009976, 2025). "Importantly, we observed a stark difference in drug sensitivity between MYCNO/E-cells and the classical RB1-deficient retinoblastoma cell line Y79, despite the latter carrying secondary MYCN amplification." (PMID 40943594, 2025). "Additionally, we investigated the relationship between the RB1 mutations and clinical presentation and outcomes, hoping that our study provides new insights to guide the management and genetic counseling of Rb patients and their at‐risk relatives." (PMID 40317918, 2025). "In addition, the CRB1, NEK7, SOX4, and NUP205 genes, identified through the genome-wide multi-omics approach in RB1-deficient tumors, have emerged as novel candidate genes associated with retinoblastoma tumorigenesis." (PMID 41009976, 2025). "Consequently, the RB1 gene cannot encode the tumor-suppressing protein, facilitating the development of retinoblastoma in a child’s retinal cells." (PMID 38540335, 2024). "Retinoblastoma (RB) is an aggressive and most common intraocular cancer in children, mainly caused by mutations in the tumor suppressor gene RB transcriptional corepressor 1 (RB1)." (PMID 38819674, 2024). "However, several publications have now shown that the analysis of cell-free DNA (cfDNA) derived from the aqueous humour (AH) of retinoblastoma patients can be used to detect somatic variation, including RB1 pathogenic variants." (PMID 38672657, 2024). "The loss of one allele of RB1 makes an individual predisposed to retinoblastoma." (PMID 39735524, 2024). "The presence of a germline RB1 mutation conveys a diagnosis of heritable retinoblastoma, which has several additional risks beyond those of the non-heritable (somatic) form, including the development of bilateral disease, as well as non-ocular second malignancies later in life." (PMID 38672657, 2024). "All patients with bilateral Rb and 10–15% with unilateral Rb have germline RB1 mutations." (PMID 39234041, 2024). "In our patient, theoretically a separate GD2-negative retinoblastoma could have developed on the basis of the RB1 germline mutation, independent from the immunotherapy." (PMID 38240863, 2024). "Although mutations in both RB1 alleles appear to be central to retinoblastoma, a small subset of unilateral tumors lack detectable mutations in this gene; instead, they exhibit significantly increased expression of the n-myc proto-oncogene (MYCN—myelocytomatosis-neuroblastoma)." (PMID 39000021, 2024). "The majority of retinoblastomas are caused by bi-allelic RB1 inactivation." (PMID 37606819, 2024). "NGS investigations, for example, have highlighted the broad mutational spectrum in retinoblastoma, including the discovery of somatic mutations in the RB1 gene and other genetic modifications that might influence disease severity and development." (PMID 38540335, 2024). "Retinoblastoma, a childhood cancer originating in the retina, is primarily attributed to pathogenic RB1 mutations The aim of this study is to conduct a mutational analysis of the RB1 gene in cases of unilateral Retinoblastoma among individuals within the Jordanian population." (PMID 39234041, 2024). "Notably, like retinoblastoma, SCLCs are frequently deficient for RB1 function, hence, in both cancers it is likely that the G1/S checkpoint is defective." (PMID 38332874, 2024). "Moreover, other cell lines derived from unilateral and bilateral retinoblastomas have provided valuable insights into the neuronal phenotypes associated with different RB1 gene mutations and/or additional non-RB1 mutations." (PMID 39000021, 2024). "Retinoblastoma arises due to mutations in the RB1 gene, recognized as a tumor suppressor gene." (PMID 39735524, 2024).
retinoblastoma (continued). "For instance, in retinoblastoma, the existence of certain mutations, such as those in the RB1 gene, might define the severity of the illness and influence treatment recommendations." (PMID 38540335, 2024). "Retinoblastoma is linked to a wide variety of RB1 gene pathogenic mutations." (PMID 38540335, 2024). "The primary association of the RB1 gene with retinoblastoma is the loss of RB1 function." (PMID 39132504, 2024). "According to the two-hit hypothesis proposed by Knudson in 1971, heritable retinoblastoma is caused by one germline mutation in the RB1 gene followed by a secondary somatic mutation that originates in retinal cells." (PMID 38540335, 2024). "Empirical evidence suggests a relationship between YST and the RB1 gene linked to retinoblastoma." (PMID 39301389, 2024). "In hereditary retinoblastoma, offspring have a 50% chance of inheriting the mutant RB1 allele." (PMID 37658463, 2023). "Retinoblastoma arises from germline mutations that deactivate one RB1 gene allele." (PMID 38201628, 2023). "In the hereditary form of retinoblastoma one mutation of RB1 gene already exists in the genome of the zygote and will be present in every cell of the body, so there is a higher risk of sustaining secondary somatic mutation in the retina and the consequent development of retinoblastoma tumor." (PMID 37658463, 2023). "The outcome of aberrant epigenomic modulation associated with the candidate genes such as RB1 involved in retinoblastoma comparing male and female may provide additional explanation with respect to the survival disadvantage of males in this condition." (PMID 36719346, 2023). "According to the Knudson hypothesis, development of retinoblastoma is initiated if both RB1 alleles have acquired disease‐causing mutations." (PMID 36910590, 2023). "Conversely, the alteration of RB1, which is a tumor suppressor gene associated with retinoblastoma and osteogenic sarcoma, may be associated with a better prognosis in GBM." (PMID 37686092, 2023). "An estimated 45% of retinoblastoma involves inherited mutation in the RB1 gene." (PMID 36719346, 2023). "Losing both alleles of the RB1 tumor suppressor gene in such susceptible developing retinal cell initiates the benign precursor, retinoma, which usually progresses to retinoblastoma with accumulation of increasing genomic changes and uncontrolled cellular proliferation." (PMID 37658463, 2023). "Though thousands of RB1 mutations have been documented, a small fraction of the unilateral retinoblastomas are found to have mutations that are yet to be identified in RB1 gene, indicating that there also exists an alternative mechanism for retinoblastoma genesis." (PMID 37667345, 2023). "Furthermore, studies on both hereditary and sporadic retinoblastoma have suggested that the polymorphic markers flanking either sides of the RB1 gene often undergo loss of heterozygosity as a result of the second hit." (PMID 37667345, 2023). "Consistent with the Knudson “two-hit hypothesis”, the development of retinoblastoma requires two mutational events in both alleles of the RB1 tumor suppression gene located in the long arm of chromosome 13 (13q14)." (PMID 37509256, 2023). "The clinical course of trilateral retinoblastoma can be unpredictable, and expressivity of germline RB1 variants may vary during development." (PMID 35340648, 2022). "Retinoblastoma arises from a cell that nearly always harbors pathogenic variants in both copies of the RB1 gene, a first and second “hit” as described by Knudson in 1971 (Knudson's two‐hit hypothesis)." (PMID 35340648, 2022). "Expression studies also showed the development of a retinoblastoma signature and upregulation of specific genes associated with retinoblastoma in late RB1 mutant organoids, since the deviation of differentiation in RB1 knockout organoids became evident only after about 40 days." (PMID 35565295, 2022). "The development of retinoblastoma is associated with inactivation of the RB1 gene." (PMID 35563062, 2022).